LNPEP (leucyl and cystinyl aminopeptidase)
Description:
Release of an N-terminal amino acid, cleaves before cysteine, leucine as well as other amino acids. Degrades peptide hormones such as oxytocin, vasopressin and angiotensin III, and plays a role in maintaining homeostasis during pregnancy. May be involved in the inactivation of neuronal peptides in the brain. Cleaves Met-enkephalin and dynorphin. Binds angiotensin IV and may be the angiotensin IV receptor in the brain.
Synonyms: IRAP; P-LAP; CAP; PLAP
Tractability: Small molecule: a drug acting on it is in phase 2 or 3 trials; a structure with a bound ligand is known; a high-quality ligand is known; it belongs to a druggable protein family. Antibody: UniProt places it where antibodies can reach, with high confidence; its Gene Ontology location is reachable by antibodies, with high confidence; UniProt predicts a signal peptide or a membrane-spanning region. PROTAC: ubiquitination databases record sites on it; its protein half-life has been measured; a small molecule that binds it is known.
Target class: Protease; Enzyme; Metallo protease; Metallo protease MAE clan; Metallo protease M1 family
Chemical probes: CHEMBL1275682, CHEMBL1277623
Gene: Protein-coding gene on chromosome 5 (96,935,394 to 97,037,513, forward strand). Ensembl gene ENSG00000113441.
Subcellular location: Cell membrane; Secreted (Leucyl-cystinyl aminopeptidase, pregnancy serum form)
Pathways (Reactome):
Immune System: Antigen processing: Ubiquitination & Proteasome degradation; Endosomal/Vacuolar pathway
Vesicle-mediated transport: Translocation of SLC2A4 (GLUT4) to the plasma membrane
Gene Ontology:
Molecular function: aminopeptidase activity; protein binding; metalloaminopeptidase activity; metallopeptidase activity; zinc ion binding
Biological process: antigen processing and presentation of exogenous peptide antigen via MHC class I, TAP-independent; cell-cell signaling; female pregnancy; negative regulation of cold-induced thermogenesis; neuropeptide catabolic process; protein polyubiquitination; proteolysis; regulation of blood pressure; antigen processing and presentation of peptide antigen via MHC class I
Cellular component: lysosomal membrane; membrane; plasma membrane; cytosol; early endosome lumen; cytoplasmic vesicle; cytoplasmic vesicle membrane; extracellular region; perinuclear region of cytoplasm
Genetic constraint (gnomAD): Loss-of-function variants: 26 observed, 59.46 expected, observed/expected ratio (o/e) 0.44, 90% interval 0.32 to 0.61. The upper end of that interval is the gene's LOEUF score, 0.61, which puts it in group 2 of 6, group 1 being the genes least tolerant of losing a copy. Missense variants: 610 observed, 757.14 expected, observed/expected ratio (o/e) 0.81, 90% interval 0.75 to 0.86. Synonymous variants: 270 observed, 274.67 expected, observed/expected ratio (o/e) 0.98, 90% interval 0.89 to 1.09.
Homologues: Orthologues: chimpanzee LNPEP (99% identical), macaque LNPEP (97% identical), rabbit LNPEP (90% identical), dog LNPEP (90% identical), pig LNPEP (89% identical), guinea pig LNPEP (88% identical), mouse Lnpep (88% identical), rat Lnpep (87% identical), tropical clawed frog lnpep (58% identical), zebrafish lnpep (54% identical), Drosophila melanogaster CG31445 (28% identical), Drosophila melanogaster SP1029 (28% identical), and 12 more. Paralogues in human: ERAP1 (41% identical), ERAP2 (39% identical), ENPEP (29% identical), ANPEP (28% identical), NPEPPS (27% identical), LVRN (26% identical), TRHDE (24% identical), RNPEPL1 (11% identical), RNPEP (11% identical), LTA4H (11% identical), AOPEP (10% identical).
Diseases named in the same sentence as LNPEP in open-access papers:
LNPEP is named in the same sentence as 38 diseases in open-access papers, as found by Europe PMC text mining. Sharing a sentence is not in itself a finding about the gene and the disease. The quoted sentences say what the papers report.
diabetes (5 papers, 2018 to 2023). "LNPEP and its genetic variants have been implicated in hypertension and diabetes because of their biological effects on vasopressin clearance, serum sodium regulation, and glucose uptake via the interaction of insulin receptor signaling with the insulin-responsive glucose transporter GLUT4." (PMID 36012327, 2022). "At the protein level, the Leucyl and cystinyl aminopeptidase (LNPEP) gene encodes a zinc-dependent aminopeptidase that facilitates the antigen transportation and processing involved in inflammatory responses in cardiovascular complications and diabetes mellitus." (PMID 36900344, 2023). "Therefore, this raises the speculation that LNPEP may have a role in the pathogenesis of both psoriasis and metabolic conditions, such as hypertension and diabetes." (PMID 36012327, 2022).
Hypertension (5 papers, 2017 to 2022). The presence of chronic increased pressure in the systemic arterial system. "A genetic variation in LNPEP was associated with plasma vasopressin clearance and serum sodium regulation, which play similar roles in the pathogenesis of hypertension and psoriasis." (PMID 30142208, 2018). "LNPEP is also involved in the final step of conversion of angiotensinogen to angiotensin IV and enhance acquisition, consolidation and recall in animal models of learning and memory; it may have bearing with REMSD-associated hypertension." (PMID 28367113, 2017).
Alzheimer disease (4 papers, 2020 to 2025). A progressive, neurodegenerative disease characterized by loss of function and death of nerve cells in several areas of the brain leading to loss of cognitive function such as memory and language. "In the process of normal aging, heightened signaling from ACE1/AGTR1 expression is predominantly countered by ACE1/AGTR2 expression, while the levels of ACE2, MAS1, and LNPEP remain constant, while in the later stages of Alzheimer’s disease, a decline in MAS1 expression emerges." (PMID 41303587, 2025).
psoriasis (4 papers, 2018 to 2022). An autoimmune condition characterized by red, well-delineated plaques with silvery scales that are usually on the extensor surfaces and scalp. "LNPEP has been involved in diabetes and associated with psoriasis, sharing the last feature with the other two aminopeptidases." (PMID 32793222, 2020). "The missense LNPEP variant A/G at rs2303138 encoding for a threonine (ACA) instead of alanine (GCA), appears to be associated with Psoriasis providing validity to the hypothesis that renin-angiotensin system can be involved in the pathology." (PMID 36203608, 2022). "More interesting, although speculative, is the hypothesis that the LNPEP specific role in the RAS can have a strong impact in psoriasis." (PMID 32793222, 2020).
Insulin resistance (3 papers, 2023 to 2026). Increased resistance towards insulin, that is, diminished effectiveness of insulin in reducing blood glucose levels. "Indeed, GLUT4 overexpression protects against insulin resistance, affects stability of LNPEP/IRAP and VAMP2 (other proteins that reside in GSVs)." (PMID 36283703, 2023).
autoimmune disease (2 papers, 2023 to 2024). A disorder resulting from loss of function or tissue destruction of an organ or multiple organs, arising from humoral or cellular immune responses of the individual to their own tissue constituents. "The ERAP1/ERAP2/LNPEP aminopeptidases are involved in antigen processing and variation is linked to multiple autoimmune diseases." (PMID 38421405, 2024). "LNPEP is an aminopeptidase that regulates hormones (i.e., arginine-vasopressin and oxytocin), and is involved in trimming peptide antigens for cross-presentation to T cells in autoimmune diseases." (PMID 37250650, 2023).
metabolic syndrome (2 papers, 2021 to 2025). A cluster of metabolic risk factors for CARDIOVASCULAR DISEASES and TYPE 2 DIABETES MELLITUS. "In conclusion, we examined 18 previously reported SNPs of metabolic syndrome in a Chinese Han population and found that 7 SNPs located in HLA, FUT2, and LNPEP were associated with PsV in Chinese Han." (PMID 34589554, 2021).
preeclampsia (2 papers, 2021). Preeclampsia is a hypertensive disorder of pregnancy that is characterized by new-onset hypertension with proteinuria presenting after 20 weeks of gestation, and depending on mild or severe forms may initially present with severe headache, visual disturbances, and hyperreflexia. "Endoplasmic reticulum aminopeptidases (ERAPs), as well as leucyl/cystinyl aminopeptidase (LNPEP), play roles in antigen processing, inflammatory response, blood pressure regulation and angiogenesis, all processes potentially implicated in preeclampsia pathophysiology." (PMID 33762660, 2021). "In this study hESF also had altered production of factors previously identified to be increased in the decidua of women with preeclampsia, including COL4A1, LNPEP, TM9SF2 and COTL1." (PMID 33898438, 2021).
alcohol dependence (1 paper, 2024). Physical and psychological dependence on alcohol. "Several experimental evidences exist to support the role of LNPEP-AGT axis in alcohol dependence." (PMID 38660223, 2024).
aortic valve disease (1 paper, 2018). "Expressions of genes in the renin-angiotensin system, especially CTSA, LNPEP, and MAS1, in the left atrium in MR patients significantly differed from expressions of these genes in aortic valve disease patients and normal controls." (PMID 30581499, 2018). "Expressions of genes in the renin-angiotensin system, especially CTSA, LNPEP, and MAS1, in the left atrium in MR patients significantly differed from those in aortic valve disease patients and normal controls, and the differences were independent of circulating angiotensin II levels." (PMID 30581499, 2018). "Additionally, in comparison with aortic valve disease patients, MR patients had significantly downregulated CTSA and LNPEP expression and significantly upregulated MAS1 expression in the left atrium." (PMID 30581499, 2018).
asthma (1 paper, 2020). "Interestingly, 4 genes of MPI, DECR2, LNPEP, and TTC19 are newly reported to be involved in severe asthma risk." (PMID 33066754, 2020). "There were 8 of 11 genes (8/11 = 72.7%) showing significantly different expression profiles between severe asthma and controls; for example, GNGT2, TLR6, TTC19, LNPEP, SLC22A5 and HLA-DQA1." (PMID 33066754, 2020).
atherosclerosis (1 paper, 2010). A disease characterized by the build-up of fatty material and calcium deposition in the arterial wall resulting in partial or complete occlusion of the arterial lumen. "In contrast, if a loss-of-function miRSNP occurred in the AGTR2, ACE2, MAS1, or LNPEP gene, a decreased incidence of hypertension, cardiac/vascular remodeling, and atherosclerosis would be expected." (PMID 20948563, 2010).
language disorder (1 paper, 2023). A category of disorders characterized by an impairment in the development of an individual's language capabilities, which is in contrast to his/her non-verbal intellect. "Significant correlations were demonstrated for the relationship between the LNPEP expression level and ADOS-2 comparative score (r = 0.26; p < 0.05), social affect subscale (r = 0.24; p < 0.05), and ADOS-2 communication and language disorder domain (r = 0.22; p < 0.05)." (PMID 37886970, 2023).
malaria (1 paper, 2019). Malaria is a serious and sometimes fatal disease caused by a parasite that commonly infects a certain type of mosquito which feeds on humans. "In conclusion, functional variants of the three aminopeptidases ERAP1, ERAP2, and LNPEP show a worldwide distribution compatible with a selective pressure by malaria." (PMID 30740100, 2019).
ovarian carcinoma (1 paper, 2023). A malignant neoplasm originating from the surface ovarian epithelium. "In cancer, LNPEP deregulation has been shown to contribute to immune infiltration of ovarian cancer." (PMID 36900344, 2023).
septic shock (1 paper, 2020). Shock caused by infection; frequently caused by gram negative bacteria, although some cases have been caused by other bacteria, viruses, fungi, and protozoa; characterized by fever, chills, tachycardia, tachypnea, and hypotension. "The genetic variation in LNPEP, which is a zinc-dependent aminopeptidase that cleaves vasopressin, was reported to be associated with 28-day mortality in septic shock." (PMID 33066754, 2020).
vascular dementia (1 paper, 2025). A degenerative vascular disorder affecting the brain. "A rise in LNPEP expression was solely linked to the progression of vascular dementia." (PMID 41303587, 2025).
tumor (4 papers, 2021 to 2024). "This combinatorial approach elicited T cells against specific neoantigens (LNPEP, NDUFS6, MYO15, and CDK15) that were positively correlated with reduced tumor burden in the treated animals." (PMID 33723260, 2021).
LNPEP also shares sentences with these, for which no sentence is quoted: cancer (2 papers); Hyperglycemia (2); ischemic stroke (2); memory impairment (2); autism spectrum disorder (1); breast carcinoma (1); cardiovascular disease (1); colon adenocarcinoma (1); colon cancer (1); dementia (1); epilepsy (1); fibromyalgia (1); HELLP syndrome (1); immune disorders (1); Obesity (1); Osteochondrosis (1); polycystic ovary syndrome (1); renal carcinoma (1); Stroke (1); type 2 diabetes mellitus (1).